FAM131A (family with sequence similarity 131 member A)
Synonyms: C3orf40; MGC21688; FLAT715; PRO1378
Tractability: No criterion of Open Targets' tractability assessment is met for any kind of drug.
Gene: Protein-coding gene on chromosome 3 (184,335,926 to 184,348,421, forward strand). Ensembl gene ENSG00000175182.
Subcellular location (Human Protein Atlas): Nucleoli rim; Mitotic chromosome
Genetic constraint (gnomAD): Loss-of-function variants: 23 observed, 39.28 expected, observed/expected ratio (o/e) 0.59, 90% interval 0.42 to 0.83. The upper end of that interval is the gene's LOEUF score, 0.83, which puts it in group 3 of 6, group 1 being the genes least tolerant of losing a copy. Missense variants: 373 observed, 478.12 expected, observed/expected ratio (o/e) 0.78, 90% interval 0.72 to 0.85. Synonymous variants: 202 observed, 206.24 expected, observed/expected ratio (o/e) 0.98, 90% interval 0.87 to 1.1.
Homologues: Orthologues: chimpanzee FAM131A (100% identical), dog FAM131A (97% identical), guinea pig FAM131A (96% identical), pig FAM131A (96% identical), macaque FAM131A (93% identical), mouse Fam131a (93% identical), rat Fam131a (92% identical), rabbit FAM131A (67% identical), tropical clawed frog FAM131A (46% identical), zebrafish fam131aa (37% identical). Paralogues in human: FAM131B (31% identical), FAM131C (25% identical).